CNR2 (cannabinoid receptor 2)
Description:
Heterotrimeric G protein-coupled receptor for endocannabinoid 2-arachidonoylglycerol mediating inhibition of adenylate cyclase. May function in inflammatory response, nociceptive transmission and bone homeostasis.
Synonyms: CB-2; CB2; CX5
Tractability: Small molecule: a drug acting on it is in phase 2 or 3 trials; a structure with a bound ligand is known; a high-quality ligand is known; it belongs to a druggable protein family. Antibody: its Gene Ontology location is reachable by antibodies, with high confidence; UniProt places it where antibodies can reach, with medium confidence; UniProt predicts a signal peptide or a membrane-spanning region. PROTAC: ubiquitination databases record sites on it; a small molecule that binds it is known.
Target class: Cannabinoid receptor; Family A G protein-coupled receptor; Membrane receptor; Small molecule receptor (family A GPCR); Lipid-like ligand receptor (family A GPCR)
Chemical probes: CHEMBL468176, JWH015, KM-233, METHYLHONOKIOL, PD084057, PD084342, PD084382, PD084742, PD134463, UCM707
Safety:
Unwanted effects reported when the protein is acted on. In parentheses: how it was acted on, where the effect was seen, and who reports it.
increased inflammation (Lynch et al. (2017): inhibition, acute dosing, nervous system, Immune; Bowes et al. (2012): inhibition, Immune)
decreased bone mass (inhibition; Immune; source: Bowes et al. (2012))
decreased inflammation (activation, acute dosing; nervous system, Immune; source: Lynch et al. (2017))
decreased pain (activation, acute dosing; nervous system, Immune; source: Lynch et al. (2017))
Gene: Protein-coding gene on chromosome 1 (23,870,515 to 23,913,362, reverse strand). Ensembl gene ENSG00000188822.
Subcellular location: Cell membrane; Cell projection, dendrite; Perikaryon
Pathways (Reactome):
Signal Transduction: Class A/1 (Rhodopsin-like receptors); G alpha (i) signalling events
Gene Ontology:
Molecular function: cannabinoid receptor activity; protein binding; G protein-coupled receptor activity
Biological process: cannabinoid signaling pathway; positive regulation of osteoblast differentiation; adenylate cyclase-activating G protein-coupled receptor signaling pathway; G protein-coupled receptor signaling pathway; G protein-coupled receptor signaling pathway, coupled to cyclic nucleotide second messenger; negative regulation of action potential; negative regulation of mast cell activation; negative regulation of synaptic transmission, GABAergic; response to amphetamine; response to ethanol; response to lipopolysaccharide; trans-synaptic signaling by endocannabinoid, modulating synaptic transmission
Cellular component: endoplasmic reticulum; plasma membrane; cytoplasm; dendrite; extrinsic component of cytoplasmic side of plasma membrane; membrane; neuronal cell body; perikaryon; postsynaptic membrane
Genetic constraint (gnomAD): Loss-of-function variants: 4 observed, 5.79 expected, observed/expected ratio (o/e) 0.69, 90% interval 0.34 to 1.53. That is too few expected variants to judge how well the gene tolerates losing a copy. Missense variants: 379 observed, 459.95 expected, observed/expected ratio (o/e) 0.82, 90% interval 0.76 to 0.9. Synonymous variants: 172 observed, 191.37 expected, observed/expected ratio (o/e) 0.9, 90% interval 0.79 to 1.02.
Homologues: Orthologues: chimpanzee CNR2 (99% identical), macaque CNR2 (96% identical), rabbit CNR2 (82% identical), dog CNR2 (82% identical), pig CNR2 (82% identical), mouse Cnr2 (80% identical), rat Cnr2 (80% identical), guinea pig CNR2 (75% identical), tropical clawed frog cnr2 (47% identical), zebrafish cnr2 (39% identical). Paralogues in human: CNR1 (42% identical), GPR6 (24% identical), S1PR1 (24% identical), S1PR5 (23% identical), GPR12 (23% identical), S1PR3 (22% identical), LPAR1 (22% identical), S1PR2 (21% identical), S1PR4 (21% identical), GPR3 (21% identical), LPAR2 (21% identical), MC1R (19% identical), and 6 more.
Diseases named in the same sentence as CNR2 in open-access papers:
CNR2 is named in the same sentence as 324 diseases in open-access papers, as found by Europe PMC text mining. Sharing a sentence is not in itself a finding about the gene and the disease. The quoted sentences say what the papers report.
Obesity (45 papers, 2009 to 2026). Accumulation of substantial excess body fat. "Obesity was associated with a modest 1.8-fold increase in Cnr2 expression in the liver, both in ob/ob and HFD-fed animals." (PMID 19513120, 2009). "We first characterized the expression of Cnr2 (encoding CB2) in the adipose tissue and in the liver, and its regulation overtime during obesity, using genetically obese leptin-deficient ob/ob mice and wild type (WT) C57Bl/6J mice fed a high fat diet (HFD) for 6 or 15 weeks." (PMID 19513120, 2009). "Subsequent experiments investigated mechanisms underlying Cnr2 impact on obesity." (PMID 19513120, 2009). "Taken together, FAAH1/FAAH2–CNR1/CNR2 genetics align with reviews positioning the ECS in obesity pathogenesis and as a therapeutic target, supporting ECS-informed precision strategies for comorbid obesity–depression." (PMID 41373743, 2025). "Six genes (CNR2, DPP4, GLP1R, SLC5A1, HTR2C, MCHR1) that encode therapeutic targets in development of type 2 diabetes or obesity." (PMID 36902588, 2023). "Insulin resistance and fat inflammation associated with obesity were improved by treatment with a CB2 receptor inverse agonist SR14528, but also in Cnr2-deficient mice." (PMID 34064024, 2021). "CNR2 was rarely examined in view of obesity, since its locations in the liver, adipose tissue, and pancreatic islet cells have only recently been defined." (PMID 33530406, 2021). "Based on the 5-HT2C receptor study, N. nucifera petal extracts showed significant agonist activity towards 5-HT2C receptor and antagonistic activity towards CNR2 indicating its role in central targets of obesity as appetite suppressant." (PMID 24348689, 2013). "Our data indicate that during obesity progression, Cnr2 expression undergoes a strong increase in adipose tissue parallel to the development of fat inflammation, and a moderate induction in the liver." (PMID 19513120, 2009). "Overall, these data indicate Cnr2 knock-out attenuates the progression of obesity by a mechanism distinct from that elicited by CB1 antagonism, possibly by increasing both lipid oxidation and fecal fat excretion." (PMID 19513120, 2009). "Overall, these results indicate that obesity enhances Cnr2 expression in the non parenchymal cell fraction of adipose tissue and liver." (PMID 19513120, 2009). "Our results indicate that fatty liver, a hallmark of obesity-associated metabolic syndrome, is enhanced by the CB2 receptor agonist JWH-133 and blunted by Cnr2 knock-out." (PMID 19513120, 2009). "According to its anti-inflammatory activity, mediated in part by CNR2 activation it could improve receptor sensitivity by reducing the inflammatory state characteristic of obesity." (PMID 41149616, 2025). "Many investigations have demonstrated the positive effects of antagonizing cannabinoid receptor 1 (CB1R) in metabolic diseases such as fatty liver disease, obesity, and diabetes mellitus, but the role of cannabinoid receptor 2 (CB2R) in such diseases is relatively unknown." (PMID 35115945, 2021).
breast carcinoma (39 papers, 2010 to 2026). "CNR2 is expressed in both ERα+ and ERα- breast cancer cells and associated with better prognosis in both subtypes." (PMID 27213582, 2017). "Overall, we show in this study that CNR2 is an important therapeutic target in ERα- and ERα+ breast cancer subtypes and its higher expression is associated with better prognosis." (PMID 27213582, 2017). "Based on breast cancer networks' centrality, we identify genes previously associated to the disease, either, generally (i.e., CNR2) or to a particular subtype (such as LCK)." (PMID 27920729, 2016). "Although CNR2 is highly expressed in the breast cancer tissues as well as breast cancer cell lines, its functional role in breast tumorigenesis is not well understood." (PMID 27213582, 2017). "Although CNR2 activation has shown significant anti-tumorigenic properties, its functional role in inhibiting breast cancer is not well understood." (PMID 27213582, 2017). "We also studied the effect of CNR2 activation on breast cancer growth using ERα+ and ERα- breast cancer mouse model systems." (PMID 27213582, 2017). "As shown, EGFR is highly expressed in different ERα- cell lines compared to ERα+ breast cancer cell lines however; CNR2 is highly expressed in both breast cancer subtypes." (PMID 27213582, 2017). "In conclusion, we show that CNR2 activation suppresses breast cancer through novel mechanisms by inhibiting EGF/EGFR and IGF-I/IGF-IR signaling axes." (PMID 27213582, 2017). "In the present study, we analyzed the anti-tumorigenic properties of CNR2 specific agonist synthetic cannabinoid (JWH-015) against different breast cancer subtypes." (PMID 27213582, 2017). "Our data support the use of CNR2 agonists as an adjuvant therapy for ERα- and ERα+ breast cancer patients." (PMID 27213582, 2017). "In the present study, we elucidated the anti-tumor role of CNR2 in ERα+ and ERα- breast cancer cells." (PMID 27213582, 2017). "Following CNR2 activation, we observed inhibition of breast cancer growth, suppression of EGF/EGFR as well as IGF-I/IGF-IR signaling pathways and their related tumorigenic events in vitro and in vivo." (PMID 27213582, 2017). "Our analysis identifies CNR2 as one of the top 30 highest degree nodes in our breast cancer subtype transcriptional networks." (PMID 27920729, 2016). "In addition, we found that higher CNR2 expression correlates with better recurrence free survival in ERα- and ERα+ breast cancer patients." (PMID 27213582, 2017). "Therefore, in this study, we analyzed the role of CNR2 activation on IGF-I-induced tumorigenic events in ERα+ breast cancer cells." (PMID 27213582, 2017). "In this study we showed that CNR2 is expressed in both ERα- and ERα+ breast cancer cells." (PMID 27213582, 2017). "CNR2 has been shown to be expressed in different cancer cells, including breast cancer." (PMID 27213582, 2017). "In addition to immune cells, CNR2 has also been shown to be expressed in breast cancer tissues and cell lines." (PMID 27213582, 2017). "CNR2 is a gene highly connected in all breast cancer networks." (PMID 27920729, 2016). "In order to illustrate how the same genes may have different roles in different breast cancer manifestations, we selected, based on their degree in each breast cancer network, the CNR2, LCK, and LUZP4 genes." (PMID 27920729, 2016). "Based on this, CNR2 might be pointed as an important gene in the general breast cancer transcriptional architecture." (PMID 27920729, 2016). "Second we analyzed the effect of CNR2 activation on IGF-I induced tumorigenesis in ERα+ and ERα- breast cancer cells." (PMID 27213582, 2017). "Our studies showed that CNR2 activation inhibited EGF and IGF-I-induced migration and invasion of ERα+ and ERα- breast cancer cells." (PMID 27213582, 2017). "In this study, we analyzed CNR2, IGF-IR and EGFR expression in ERα- and ERα+ breast cancer cells." (PMID 27213582, 2017).
breast carcinoma (continued). "In addition, we show, for the first time, that CNR2 activation inhibits the activation of EGFR/IGF-IR signaling pathways and EGF/IGF-I-induced tumorigenic events in ERα- and ERα+ breast cancer subtypes in vitro and in vivo." (PMID 27213582, 2017).
Anxiety (36 papers, 2014 to 2026). Intense feelings of nervousness, tension, or panic often arise in response to interpersonal stresses. "Elsewhere, after the generation of a CB2-knock-out zebrafish, the resulting homozygote (cnr2 upr1/upr1) larvae were shown to be characterized by lower swimming performances and increased anxiety-like behaviors." (PMID 36009367, 2022). "Poly I:C, that is known known to induce immune stress, reduced the locomotor activity of mice and provoked anxiety-like behavior, which was apparent in the Cnr2 heterozygotes than in the wild type mice." (PMID 30042304, 2018). "Treatment with Poly I:C reduced the percent time spent in the open section of the Zero maze, indicating an anxiety-like behavior that was enhanced in the heterozygote Cnr2 knockout mice than in the wild type mice." (PMID 30042304, 2018). "In this study, Poly I:C, known to produce immune stress, decreased the locomotor activity of mice and increased their anxiety-like behavior, which was apparent in the Cnr2 heterozygotes than in the wild type mice." (PMID 30042304, 2018). "It is likely that bidirectional modulation of CNR2 and FAAH genes would likely increase social interaction and reduce anxiety and neuroinflammatory responses in autistic children." (PMID 38744725, 2024). "In agreement with this, another study using mice lacking the CB2R gene (Cnr2–/– mice) revealed that CB2R gene knock out mice developed higher levels of anxiety-like behavioral responses in both tests." (PMID 35774086, 2022). "Beyond CNR1, eCB system could exert actions on other targets including CNR2, transient receptor potential vanilloid receptor type 1 (TRPV1), or cyclooxygenase-2 (COX2) to participate in improvement of anxiety." (PMID 33178009, 2020). "We found that Cnr2 and Tlr4 genes related to neuroinflammation were robustly upregulated in the ACC and amygdala of aging mice, suggesting that these two genes play an important role in the genesis of depression and anxiety during aging." (PMID 33015035, 2020).
depression (31 papers, 2008 to 2025). "Further studies in the Japanese population showed that Q63R polymorphism of the CNR2 gene is linked with alcoholism and depression." (PMID 38744725, 2024). "Polymorphisms in the CNR2 gene have been linked to pain, autoimmune disorders, and depression in humans." (PMID 37185752, 2023). "Several studies have reported associations between genetic variants of the cannabinoid receptor type 1 and type 2 genes (CNRs; CNR1 and CNR2) and a susceptibility to develop depression." (PMID 35628337, 2022). "A relationship between genetic variants in cannabinoid receptor type 1 and type 2 genes (CNR; CNR1 and CNR2) and susceptibility to depression was also reported." (PMID 36430254, 2022). "To summarize, genetic variations in CNR2 are associated with the vulnerability to depression; relating this marker to depression-associated brain dysfunction may potentially improve the diagnosis and treatment for depression." (PMID 35628337, 2022). "Although CB2R is relatively expressed less in brain than CB1R, it is worth mentioning here that a polymorphism in the CNR2 gene encoding CB2R is linked to schizophrenia and is associated more efficiently with depression in the Japanese population." (PMID 39796008, 2024). "Another piece of evidence against the relationship between depression and CNR1 is a recent meta-analysis, which assessed the relation between CNR1 and CNR2 polymorphisms and depressive disorder susceptibility." (PMID 35628337, 2022). "Summary of the modulatory effects of cannabinoid receptor 2 (CB2r) on neuroinflammation in depressive disorders." (PMID 35492718, 2022). "Β- caryophyllene and dibutyl phthalate could directly act on CHRM1, FAAH, CNR2, SLC6A2, and SLC6A3, which were associated with anesthesia, attention deficit hyperactivity disorder, and major depressive disorder." (PMID 40729010, 2025). "The evidence presented suggests that overexpression of CNR2 gene could be a potential therapeutic approach for treating inflammation and depression in autistic children." (PMID 38744725, 2024). "A significant correlation was observed between variations at CNR2 rs2501432 and depression." (PMID 37185752, 2023). "Although polymorphism of the CNR2 gene is not well studied, but it may be associated with depression in humans." (PMID 38744725, 2024). "A recent meta-analysis indicated that CNR1 rs1049353 or AAT triplet repeat sequence polymorphisms were not relevant for depression susceptibility, but CNR2 rs2501432 gene polymorphisms may be strongly correlated with depression." (PMID 36430254, 2022).
glioma (28 papers, 2006 to 2025). A benign or malignant brain and spinal cord tumor that arises from glial cells (astrocytes, oligodendrocytes, ependymal cells). "Although cannabinoid receptor 2 (CB2R) stimulation exerts anti-tumor action in glioma cells by regulating cellular proliferation, differentiation, or apoptosis, selective CB2R agonist alone does not achieve a satisfactory therapeutic outcome." (PMID 33330047, 2020).
schizophrenia (28 papers, 2010 to 2025). A major psychotic disorder characterized by abnormalities in the perception or expression of reality. "In Japanese schizophrenia patients, the CNR2 polymorphisms rs12744386 and rs2501432 were found to be significant, whereas the CNR2 polymorphisms rs2501432 and rs22229579 were found to be significant in the Han ethnic population of China." (PMID 35055161, 2022). "Additionally, two single nucleotide polymorphisms (SNPs) in the CNR2 gene were found to be associated with increased susceptibility to developing schizophrenia." (PMID 36033626, 2022). "Specific CNR2 polymorphisms leading to a loss of function (R63 allele of rs2501432 (R63Q), the C allele of rs12744386, and the haplotype of the R63-C allele) were significantly increased in patients with schizophrenia." (PMID 35563156, 2022). "In fact, genome-wide association studies (GWAS) from a population-based United Kingdom Biobank sample revealed shared genetic liability between psychotic experiences and schizophrenia and identified a locus in the CNR2 gene to be significantly associated with distressing psychotic experiences." (PMID 36033626, 2022). "However, CNR2 polymorphisms rs35761398 and rs12744386 were recently associated with schizophrenia and cannabis dependence comorbidity." (PMID 35563156, 2022). "Interestingly, targeted deletion of the CNR2 gene causes schizophrenia-related behaviors in mice." (PMID 24427139, 2014). "This corroborates with our recent study showing increased prelimbic cnr2 expression in a rat model for schizophrenia that was restored by chronic treatment with URB597." (PMID 36555739, 2022). "CNR2 gene expression was shown to be significantly reduced in the peripheral mononuclear blood cells of patients with schizophrenia." (PMID 35055161, 2022). "In humans, the polymorphism of CNR2, which encodes CB2R, is related to schizophrenia, depression, and bipolar disorder." (PMID 26819779, 2016). "CNR2 expression resulted also significantly reduced in PBMCs of individuals with schizophrenia even if others reported an increase in mRNA levels of this receptor in schizophrenia as well as in autistic children." (PMID 38409080, 2024). "As introduced earlier, the abnormality of CNR2 in humans is related to schizophrenia and CB2R KO mice display schizophrenia-like phenotypes, for example, impairment in sensory-motor gating and an increase in depressive behavior." (PMID 26819779, 2016).
colitis (26 papers, 2009 to 2024). Inflammation of the colon. "Furthermore, our previous studies demonstrated that inducing autophagy by activating the cannabinoid receptor 2 inhibited NLRP3 inflammasome activation in colitis and EAE mouse models." (PMID 38354108, 2024). "In our previous work, we demonstrated that activation of cannabinoid receptor 2 could induce autophagy, which subsequently led to the inhibition of NLRP3 inflammasome in CNS in EAE as well as colitis mice models." (PMID 28559895, 2017).